PTX3 (pentraxin 3)
Diseases named in the same sentence as PTX3 in open-access papers (continued):
Sharing a sentence is not in itself a finding about the gene and the disease.
atherosclerosis (continued). "Increased expression of PTX3 has previously been found in vascular inflammation, atherosclerosis and in the process of restenosis after angioplasty." (PMID 24060373, 2013). "Important pieces of knowledge regarding PTX3 behavior in cardiovascular diseases, such as atherosclerosis and acute myocardial infarction (AMI), have been gained in the last ten years." (PMID 22577258, 2012). "During the course of aging, PTX3−/− apoE−/− mice develop, in line with expectations, increasing atherosclerosis as a function of time." (PMID 22577258, 2012). "Recently, pentraxin-3 (PTX3) has been proposed to be a specific marker of vascular inflammation, yet its association with atherosclerosis is still unclear." (PMID 22319633, 2012). "Measures of carotid and femoral artery atherosclerosis according to PTX3 tertile groups in the Bruneck Study." (PMID 22319633, 2012). "In future work, the contribution of CS-exposure to the development of atherosclerosis in Ptx3/ApoE double KO mice has to be elucidated." (PMID 20920344, 2010). "Furthermore, it was reported that PTX3 was positively correlated with atherosclerosis markers in patients with T1D." (PMID 39657836, 2025). "Moreover, there is a positive correlation between PCSK9 (proprotein convertase subtilisin/kexin type 9), a regulator of hepatocyte LDL receptor, and PTX3, confirming once again its clinical use in assessing atherosclerosis." (PMID 36553147, 2022). "Upregulated genes in BBA-derived VSMCs are related to arterial mineralization and atherosclerosis, such as PTX3, SPP1, LOX, etc., whereas vasodilation and physiological regulatory genes such as MGP, ACTA2, and MYL9 were conversely enriched in conventional IA-derived VSMCs." (PMID 35874788, 2022). "PTX3 is a recognized marker of vascular mineralization and atherosclerosis." (PMID 35874788, 2022). "We believe that PTX3 may play different roles in atherosclerosis between stroke patients and the general population, which can result from complex effects of PTX3 upon the vasculature due to the involvement of multiple pathways." (PMID 33210471, 2021). "PTX3 can reflect different aspects of atherosclerosis‐related inflammation than that revealed by CRP and may thus provide additional insight into atherosclerosis development and progression." (PMID 33210471, 2021). "The evaluation of PTX3 levels has been proposed as an important sensitive tool to predict cardiovascular mortality risk in patients with advanced CKD and to identify and treat early-stage subclinical atherosclerosis in these patients." (PMID 34285273, 2021). "The missing link between the genetic variants determining PTX3 and ficolin-2 levels with the risk of MI suggests that they act as markers of active atherosclerosis and complement activity rather than causal factors." (PMID 28216633, 2017). "PTX3 binds to activated platelets and reduces inflammation in the cardiovascular bed, and might be a novel marker for subclinical atherosclerosis." (PMID 28977161, 2017). "Finally, PTX3 has been indicated also as a marker of neo-intimal thickening after vascular injury, since elevated levels of PTX3 have been found in patients with atherosclerosis, after 15 min from coronary stenting." (PMID 27559355, 2016). "Further studies are needed to clarify the molecular mechanisms that link PTX-3 to atherosclerosis." (PMID 26697221, 2015). "Moreover, these two conditions have an additive role in the progression of carotid atherosclerosis and in blood levels of inflammatory markers for atherosclerosis, such as interleukin-6 and pentraxin-3." (PMID 26697221, 2015). "So far, the precise role of PTX3 in atherosclerosis is unclear." (PMID 25014007, 2014). "First, direct assessment of atherosclerosis severity was not available at the time of the study, although a positive relationship between the extension of vascular disease and PTX3 levels in subjects with cardiovascular risk factors is well established." (PMID 25014007, 2014).
atherosclerosis (continued). "PTX3 is strictly associated with vascular disease, as high levels have been detected in atherosclerotic plaques and in plasma from patients with elevated LDL cholesterol and extensive atherosclerosis." (PMID 25014007, 2014). "We have previously shown that patients with RA of short duration exhibit endothelial activation (expressed by increased level of soluble sVCAM-1, MCP-1, and von Willebrand factor and pentraxin-3) that is an important factor in the development of atherosclerosis." (PMID 25126574, 2014). "Thus, the role of PTX3 in the pathogenesis of obesity, metabolic syndrome, diabetes mellitus, and atherosclerosis remains uncertain." (PMID 24705587, 2014). "Level of PTX3 is independently associated with atherosclerosis and manifest cardiovascular disease but not early vessel pathology." (PMID 22319633, 2012). "Moreover, PTX3 level correlated with the severity of carotid and femoral atherosclerosis and was highest in individuals with multiple vascular territories affected." (PMID 22319633, 2012). "In addition, PTX3 level increased with the number of vascular beds involved in the atherosclerosis process (P<0.001)." (PMID 22319633, 2012). "There are even first hints that PTX3 might play an as yet unrecognized protective role in atherosclerosis and its complications." (PMID 22577258, 2012). "Double-knockout mice lacking PTX3 and apolipoprotein E (ApoE) in combination with an atherogenic diet are susceptible for atherosclerosis." (PMID 20920344, 2010). "In addition, pentraxin-3 affects the lipid metabolism in human macrophages by stimulating the uptake of oxLDL and inhibiting cholesterol efflux, thereby contributing to the initial stages of EC dysfunction and consequent atherosclerosis." (PMID 37194071, 2023). "PTX-3 was not only the first identified classic pentraxin but also an acute-phase reaction protein in inflammation, which is capable of binding to multiple soluble receptors and ligands and is involved in multiple biological effects, such as immune defense, inflammation, and atherosclerosis." (PMID 30992732, 2019). "However, one must acknowledge that, while the functional role of PTX3 in some vascular disorders, i.e., atherosclerosis and MI, has been well-described, in HF and CA, PTX3 has been explored only as a biomarker and there is little evidence of its functional involvement." (PMID 31057548, 2019). "Thus, PTX3 is increasingly emerging as a potential biomarker of atherosclerosis and CVD8." (PMID 28216633, 2017). "Moreover, evidence from literature has suggested a link between PTX3 and atherosclerosis." (PMID 26903710, 2016). "In addition, PTX3 may inhibit complement activation and increase the progression of atherosclerosis." (PMID 26842615, 2016). "PTX3 is involved in the maintenance of vascular homeostasis: it plays a protective role in various vessel diseases in which inflammation and vascular remodelling both contribute to the clinical outcome, such as atherosclerosis or the response to balloon angioplasty." (PMID 25394473, 2014). "Furthermore, neutrophils and monocytes/macrophages could contribute to the large amount of PTX3 observed in arterial thrombi and aortic tissue in patients with different degrees of atherosclerosis with acute myocardial infarction." (PMID 23690668, 2013). "Furthermore, PTX3 displays a predilection to segments of vascular or synovial inflammation in rheumatic diseases, the pathogenesis of which is supposed to have much in common with that of atherosclerosis." (PMID 22577258, 2012). "Further investigations are necessary to fully elucidate the involvement of PTX3 in the pathophysiology of atherosclerosis and the influence of different PCSK9 inhibitors on PTX3 plasma levels." (PMID 40573228, 2025). "Lipid markers, including Lp-PLA2 and oxylipins, elucidate lipid metabolism’s contribution to atherosclerosis, while inflammatory biomarkers like TNFα, IL-6, GDF-15, and PTX3 highlight the role of chronic inflammation in CVD progression." (PMID 40244022, 2025).
atherosclerosis (continued). "PTX3 has been identified as an early marker of vascular inflammation and endothelial dysfunction, notably in conditions such as AMI and atherosclerosis." (PMID 40242450, 2025). "Cytokines, including pentraxin 3 (PTX3), copeptin, lipoprotein(a) [Lp(a)], and matrix metalloproteinase-9 (MMP-9), influence atherosclerosis progression and plaque vulnerability." (PMID 38929525, 2024). "Herein, we aimed to assess the effect of M694V homozygosity on the early markers of CVD (FMD and PTX3 for endothelial dysfunction and cIMT and FGF23 for atherosclerosis) in patients with FMF-related amyloidosis." (PMID 35629299, 2022). "Some studies have also reported a decrease in Pentraxin -3 (PTX3), which is structurally related to CRP and plays a regulatory role in inflammation with a possible protective effect against atherosclerosis and cardiovascular risks." (PMID 33800490, 2021). "Plasma levels of PTX-3 were elevated in TA and GCA, as well as in other vascular conditions such as atherosclerosis, acute myocardial infarction and following acute vascular damage during stenting procedures." (PMID 33569633, 2021). "Genes such as COMP (cartilage oligomeric matrix protein), CHI3L1, PLA2G2A, P2RY12, CR1, HPSE (heparanase), PTX3 and SERPINE1 were related to atherosclerosis." (PMID 34218797, 2021). "This novel and sex-related role for secreted proteins, and mainly for PTX3, may open the way to the discovery of still unknown sex-specific mechanisms and pharmacological targets for the prevention and treatment of endothelial dysfunction at the onset of atherosclerosis and cardiovascular disease." (PMID 33413676, 2021). "Importantly, PTX3 has been described as a multifaceted modulator which appears to be able to bind to multiple ligands and exert a complexity of both protective and harmful effects in different clinical settings including inflammation, innate immunity, tissue repair, atherosclerosis, and CVD." (PMID 31316299, 2019). "PTX3 and LDL-C have been shown to correlate with severity of coronary artery disease in patients with intermediate to high atherosclerosis severity." (PMID 31998222, 2019). "In obesity-induced atherosclerosis, high-density lipoprotein (HDL) is able to promote high expression levels of PTX3 by activating the PI3K/AKT (phosphatidylinositol-3-kinase/protein kinase-B) pathway, leading to an increase in the expression of APO-1 in vivo." (PMID 28770376, 2017). "However, it has not yet been evaluated whether plasma PTX3 levels are associated with subclinical atherosclerosis in patients with NAFLD, so far." (PMID 26997950, 2016). "The aims of this study were thus to evaluate levels of inflammatory markers of atherosclerosis, such as IL-6, TNF-α, CRP, and PTX-3 in a sample of OSA patients; to assess the correlation between carotid IMT and levels of these inflammatory markers." (PMID 24481114, 2014). "Furthermore, there is evidence that PTX-3 enhances apoptotic cells clearance, and therefore contributes to reduce the size of atherosclerotic lesions; indeed, it is largely known that an efficient apoptotic cells clearance limits the development of atherosclerosis." (PMID 24481114, 2014). "In atherosclerosis, high-density lipoprotein (HDL) induces the expression of PTX3 by activating a PI3K/Akt-dependent pathway in endothelial cells." (PMID 23755050, 2013). "On one hand, PTX3 has cardioprotective and atheroprotective roles, as described in mouse models of acute myocardial infarction (AMI) and atherosclerosis, respectively." (PMID 20920344, 2010). "Pentraxin 3 (PTX3) is related to heart failure and atherosclerosis." (PMID 35888704, 2022). "Interestingly, PTX3 regulates angiogenesis via FGF2, thus interfering with a variety of conditions, including ontogenesis, growth, inflammation, tissue repair, atherosclerosis, and tumors." (PMID 27559355, 2016).
atherosclerosis (continued). "The present study does not allow to elucidate the role of PTX-3 in atherosclerosis; nevertheless, the presence of a significant correlation with carotid intima-media thickness suggest that PTX-3 can be considered as a marker of vascular damage in OSA subjects." (PMID 24481114, 2014). "In summary, PTX3 serum level is a marker of advanced and symptomatic but not early atherosclerosis in humans." (PMID 22319633, 2012). "Several extracellular matrix molecules, besides PTX3, are able to trap FGF2 in the extracellular environment (such as thrombospondin-1 and cleaved syndecan) and modulate its effects during processes such as inflammation, wound healing, atherosclerosis, and neoplasia." (PMID 29556234, 2018). "Actually, the role of PTX3 in the atherosclerosis is not well-understood." (PMID 27559355, 2016). "Thus, it suggests that PTX3 may become a useful marker to understand the development of fibrosis in patients with NAFLD and a biochemical indicator of increased arterial stiffness in subclinical atherosclerosis." (PMID 26997950, 2016). "Moreover, double-knockout mice, lacking PTX3 and apolipoprotein E, exhibit increased atherosclerosis and macrophage accumulation in atherosclerotic lesions compared with that observed in apolipoprotein E only knockout mice, suggesting that PTX3 possesses a cardiovascular protective function." (PMID 28955836, 2016).
acute myocardial infarction (67 papers, 2008 to 2026). Necrosis of the myocardium, as a result of interruption of the blood supply to the area. "Circulating PTX3 levels have been observed as a sensitive biomarker for risk stratification in conditions such as acute myocardial infarction, heart failure, renal injury, and acute lung injury." (PMID 38110934, 2023). "Studies in patients at risk for myocardial infarction reported that this PTX3 polymorphism is associated with higher plasma PTX3 levels in individuals with AA genotype of rs230561925." (PMID 34285273, 2021). "In accordance with this possibility, increased tissue damage was observed in PTX3 deficient mice in myocardial infarction model, in addition to an enhanced survival of PTX3 transgenic mice upon endotoxemia." (PMID 26644796, 2015). "Fibrocytes are found in pulmonary fibrosis lesions, and PTX3 accumulation is associated with fibrotic lesions in asthma and myocardial infarction." (PMID 25774777, 2015). "But the intriguing possibility that PTX3 is a risk predictor of future cardiovascular complications (e.g., acute myocardial infarction) remains obscure." (PMID 24705587, 2014). "So far, PTX3 level has been proposed as a risk predictor for acute myocardial infarction and biomarker of adverse outcome in patients with unstable angina pectoris, myocardial infarction and heart failure." (PMID 22319633, 2012). "Intriguingly, we found a number of novel CS/CPB–induced genes such as PTX3, Toll-like receptors and resistin that were only recently linked to cardiac pathology, in particular myocardial infarction." (PMID 21048961, 2010). "Besides infectious diseases, PTX3 has hence been studied extensively in cardiovascular disease and association with clinical outcomes was found in myocardial infarction, heart failure, and cardiac arrest." (PMID 35326373, 2022). "Additionally, an association of PTX3 with myocardial injury following ischemia has been shown in animal studies and in humans with fatal myocardial infarction." (PMID 35326373, 2022). "Increased PTX3 levels are associated with the incidence of cardiovascular disease, and PTX3 is recognised as an independent predictor of mortality at 3 months after acute myocardial infarction." (PMID 25616391, 2015). "The knockout of PTX3 has been shown to promote recovery after myocardial infarction by inhibiting fibrosis." (PMID 40093897, 2025). "PTX3 is also a biomarker of the diabetic vasculopathy, with elevated serum levels being identified in carotid and coronary plaques in patients with acute myocardial infarction." (PMID 35563387, 2022). "In this study, we analyzed dynamic changes in one well-established (CRP) and two more novel (PTX3, neprilysin) biomarkers in acute myocardial infarction." (PMID 35203485, 2022). "Patients with acute myocardial infarction show an early peak in PTX3 levels observed within 6–8 h of symptom onset to values 3–5 times the normal range." (PMID 35989325, 2022). "In peripheral blood tissue, PTX3 was found to be significantly elevated in human patients with heart failure and acute myocardial infarction, contributing to the occurrence of cardiovascular events and cardiovascular risk factors." (PMID 35898935, 2022). "After myocardial infarction, PTX3 plasma levels peaked at 7.5 h, providing evidence that PTX3 is a strong prognostic marker for cardiovascular mortality." (PMID 36574434, 2022). "As with LGALS3, PTX3 expression was found to be increased under diseased conditions, and pentraxin-3 has been defined as a novel and independent prognostic marker of mortality after acute myocardial infarction (AMI) and IS." (PMID 34946887, 2021). "Pentraxin 3 (PTX3) is a protein that is known to employ anti-inflammatory as well as protective effects in peripheral inflammatory conditions such as infections, acute myocardial infarctions, and inflammation of the lungs." (PMID 35095896, 2021).